SETDB1 (SET domain bifurcated histone lysine methyltransferase 1)
Diseases named in the same sentence as SETDB1 in open-access papers (continued):
Sharing a sentence is not in itself a finding about the gene and the disease.
lung carcinoma (32 papers, 2014 to 2025). "On the other hand, SETDB1 has also been reported to mediate methylation of Akt and promote its K63-linked ubiquitination in lung cancer." (PMID 37915765, 2023). "Here, we summarize the biological functions of SETDB1 and its therapeutic relevance in lung cancer and mesothelioma, describing possible diagnostic and therapeutic prospects." (PMID 34299035, 2021). "SETDB1 enzyme deficiency was reported to be unable to inhibit the migration ability of lung cancer cells, indicating that the antitumour function of SETDB1 in lung cancer cells is dependent on its histone H3K9 methylase activity." (PMID 34299035, 2021). "We identified interesting molecular signatures associated with the roles of SETDB1 in lung cancer and hope that these findings facilitate the development of biologically relevant targeted therapies for particular lung cancer types." (PMID 33343623, 2020). "We identified interesting molecular signatures associated with the possible roles of SETDB1 in lung cancer." (PMID 33343623, 2020). "A similar mechanism (association between Smad3 and SETDB1 to repress gene expression) has also been shown to suppress lung cancer metastasis through repressing ANXA2 expression and repress IL-2 gene expression in activated T cells." (PMID 32114978, 2020). "Different expression levels of SETDB1 in different cancer types and stages indicate that SETDB1 may be a diagnostic biomarker in certain cancers, such as lung cancer and mesothelioma." (PMID 34299035, 2021). "SETDB1 has been implicated in promoting tumorigenesis in melanoma and lung cancer." (PMID 32114978, 2020). "Based on the pattern of methylation change in the lung cancer samples, we assume that SETDB1 overexpression is associated with the uniform change in genomic methylation (i.e., methylation loss) in the ADCs but not in the SCCs, and the underlying mechanism of this is yet to be elucidated." (PMID 33343623, 2020). "Since tobacco use is the leading cause of lung cancer, we next investigated whether the expression of SETDB1 is associated with smoking in NSCLC." (PMID 31398867, 2019). "Epigenetic deregulation of SETDB1 expression seems to be involved in various types of cancers, including melanoma, hepatocellular carcinoma, ovarian, lung cancer, colorectal and breast cancer." (PMID 39945463, 2025). "At the opposite, experiments on lung cancer cells have shown that inhibition of SETDB1 using the CRISPR/Cas9 system decreases proliferation capacity but unexpectedly increases migration and transformation activities." (PMID 39945463, 2025). "Other studies have shown, that SETDB1, as a major histone methyltransferase with oncogenic activity in lung cancer cells, drives lung cancer phenotype by regulating epigenomic landscapes, 3D genome organization, and overall nuclear structure and mechanics." (PMID 38525426, 2024). "SETDB1 has been found to be amplified in lung cancer cell lines and primary tumors, resulting in increased mRNA and protein levels, which contributes to tumor growth and invasion." (PMID 38057834, 2023). "Overexpression in lung cancer and inactivation in mesothelioma indicate disparate functions of SETDB1 in different types of cancers." (PMID 34299035, 2021). "In addition, SETDB1 exploits its gene-silencing function through protein complexing, indicating regulation of SETDB1-associated molecular signatures could facilitate the development of targeted therapies for particular types of lung cancer." (PMID 34299035, 2021). "In lung cancer, SETDB1 was found to be both upregulated and downregulated, indicating that it holds dual functions in specific cancer types." (PMID 34299035, 2021). "In lung cancer, hyperactivation of SETDB1 was found to influence various pathways, such as the WNT, MAPK, Toll-like receptors (TLRs), focal adhesion, and JAK-STAT pathways." (PMID 34299035, 2021).
lung carcinoma (continued). "Amplified and overexpressed expression of SETDB1 generally exists in lung cancer, while inactivation of SETDB1 was discovered in mesothelioma, indicating that SETDB1 plays disparate roles in different cancer types." (PMID 34299035, 2021). "Overexpression and amplification of SETDB1 accelerate the development and tumour invasion of lung cancer and are also related to poor prognosis of overall survival and shorter disease-free survival in NSCLC patients." (PMID 34299035, 2021). "We summarize the oncoprotein and tumour suppressive roles of SETDB1 in lung cancer in the following sections." (PMID 34299035, 2021). "Lung cancer is the most common type of cancer worldwide in which SETDB1 amplification and H3K9 hypermethylation have been indicated as potential tumourigenesis markers." (PMID 34299035, 2021). "SETDB1 expression is dramatically decreased in highly metastatic sublines of the CL1 lung cancer cell line." (PMID 34299035, 2021). "As with many other oncogenes, SETDB1 is also regarded as a crucial inhibitor in lung cancer at certain stages." (PMID 34299035, 2021). "In the context of lung cancer, amplification or overexpression of SETDB1 plays an oncogenic role, providing an opportunity to target SETDB1 with inhibitors in clinical treatment." (PMID 34299035, 2021). "As a histone lysine methyltransferase, aberrant SETDB1 expression is frequently found in lung cancer and malignant mesothelioma." (PMID 34299035, 2021). "An oncogenic role of SETDB1 has been demonstrated in lung cancer and prostate cancer, in which SETDB1 is involved in the positive stimulation of WNT signaling." (PMID 34108525, 2021). "In a study on lung cancer, SETDB1 overexpression correlated with the clonogenicity and tumor size in a xenograft model." (PMID 33343623, 2020). "In lung cancer, the expression of SETDB1 is upregulated in cancer tissues and cooperates with SMAD2/3 to inhibit lung cancer metastasis." (PMID 32393761, 2020). "Most interestingly, an amplification of the SETDB1 gene was also described in lung cancer, in which SETDB1 is considered as a pro-oncogene able to increase tumor invasion." (PMID 31398867, 2019). "Although SETDB1 has been suggested to have an oncogenic impact in lung cancer based on transcription level or expression data, our results suggest that at least some of the identified SETDB1 somatic mutations are probably loss of function mutations." (PMID 26824986, 2016). "The inhibition of SETDB1 expression in SETDB1-gene-amplified lung cancer cells reduced tumor growth in cell culture and nude mice models, whereas its overexpression increased tumor invasiveness." (PMID 25537518, 2015). "Amplification of the SETDB1 gene in lung cancer was recently shown to contribute to lung tumorigenesis, and shRNA-mediated depletion of SETDB1 in amplified cells reduced tumor growth in a mouse xenograft model." (PMID 25484917, 2014). "Moreover, new research shows that SETDB1 fuels the phenotype of lung cancer by modulating the epigenome and resists anti-CTLA4 and anti-PD1 combination therapy." (PMID 36092910, 2022). "Similarly, ferroptosis also take part in the pathway that SET domain bifurcated 1 (SETDB1) regulates epithelial-mesenchymal transition (EMT) in lung cancer." (PMID 35784729, 2022). "Furthermore, the overexpression of SETDB1 promotes the growth of lung cancer cells as well as the invasiveness potential of tumourous cells in vitro and in vivo in nude mouse models." (PMID 34299035, 2021). "We herein summarize the SETDB1 mechanisms previously discussed in lung cancer." (PMID 34299035, 2021). "A recent report found that the reverse expression of SETDB1 and FosB may be the potential pathway of cell proliferation and diffusion in lung cancer." (PMID 34299035, 2021). "SETDB1 targeting in lung cancer has been attempted through the use of the methyltransferase inhibitor DZNep, which downregulates SETDB1 expression and H3K9me3 levels, decreasing lung cancer cell growth and increasing apoptosis." (PMID 34440561, 2021).
lung carcinoma (continued). "Unfortunately, however, the TE expression data were unavailable in the RNA-seq datasets analyzed in this study; thus, we were unable to investigate the extent to which the genomic TE expression would be affected and altered by SETDB1 overexpression in lung cancers." (PMID 33343623, 2020). "SETDB1 levels are greatly increased in numerous cancers, including lung cancer, and is an important epigenetic regulator involved in control of histone methylation in tumorigenesis, dysregulation of histone methylation, and aberrant miRNA profiling, contributing to tumorigenesis and progression." (PMID 32391354, 2020). "Furthermore, SETDB1 is overexpressed in lung cancer and silences certain genes by direct interaction with the DNA methyltransferase DNMT3A, and both are implicated in epithelial-to-mesenchymal transition (EMT) and metastasis." (PMID 31398867, 2019). "Transcription of SETDB1 can be regulated by DZNep and its expression was decreased in lung cancer." (PMID 31428579, 2019). "Similarly Paclitaxel 12 is a, widely used anti-cancer drug and downregulation of SETDB1 at the transcriptional level by 12 resulted in the death of human lung cancer cells." (PMID 31428579, 2019). "Finally, three studies reported results highlighting the possible therapeutic targeting of SETDB1 during lung cancer treatment." (PMID 31398867, 2019). "Here, we tested the clinical significance of SETDB1 mRNA level in lung cancer subtypes." (PMID 31398867, 2019). "The SETDB1 gene is amplified in human lung cancer, where the protein plays a driver role." (PMID 31398867, 2019). "Here, we asked whether SETDB1 overexpression was related to the clinical features of lung cancer patients with two major types of NSCLC, namely, adenocarcinoma and squamous cell carcinoma." (PMID 31398867, 2019). "The SETDB1 gene was found to be amplified in lung cancer cell lines and primary tumors." (PMID 31398867, 2019). "SETDB1 has been reported to be amplified and a potential oncogene in lung cancer." (PMID 26824986, 2016). "SETDB1, a histone methyltransferase, is reportedly a potential oncogene in lung cancer." (PMID 26824986, 2016). "Therefore, to comprehensively understand the lung cancer methylome and the implication of SETDB1 overexpression, we should first determine the methylation change occurring in the genic loci and in the various genomic repeats that occupy almost half of the genome." (PMID 33343623, 2020). "Importantly, previous studies demonstrated that SUV39H1 and SETDB1 are highly expressed in lung cancer, and the dysregulation of SUV39H1 and SETDB1 accelerates the development of lung cancer, suggesting that aberrant H3K9 methylation plays a critical role in lung carcinogenesis." (PMID 30054425, 2018). "Our findings suggest that five genes (SETDB1, TWIST1, HDAC1, SP1, and GRIA2) are likely involved in the dystropic relationship observed between Huntington’s disease and non–small cell lung cancer." (PMID 40843670, 2025). "Other HMTs, such as SET domain containing 8 (SETD8), SET and MYND domain containing 3 (SMYD3), SETDB1, and PRMT5, are also overexpressed in lung cancer, correlating with the tumor’s aggressiveness and clinical characteristics." (PMID 38525426, 2024). "Further studies found that SETDB1 functionally cooperated with the TGFb-regulated complex SMAD2/3 to inhibit the expression of Annexin A2 (ANXA2), which plays a crucial role in lung cancer metastasis." (PMID 34299035, 2021). "SETDB1 hyperactivation affects various signaling pathways, such as the WNT, MAPK, Toll-like receptors (TLRs), focal adhesion, and JAK-STAT pathways in lung cancer cells." (PMID 31398867, 2019). "SETDB1 hyperactivation affects various signaling pathways such as WNT, MAPK, Toll-like receptors (TLRs), focal adhesion, and JAK-STAT pathways in lung cancer cells." (PMID 31398867, 2019).
lung carcinoma (continued). "And a recent study elucidated that SETDB1, another H3K9-specific histone methyltransferase, accelerated lung cancer tumorigenesis by regulating the Wnt signaling pathway." (PMID 30348169, 2018). "Setdb1 (also called Eset and KMT1E) is amplified in melanoma and overexpressed in lung cancer." (PMID 27790377, 2016). "Finally, SETDB1 protein levels were higher in tissues from lung cancer patients compared to non-tumor tissues." (PMID 31398867, 2019). "Indeed, in addition to its best-known target, namely, H3K9, it is also known that SETDB1 methylates many other non-histone substrates with high relevance to lung cancer." (PMID 31398867, 2019). "Moreover, the reverse expression of SETDB1 and FosB mediated by MEK/ERK2 in anticancer drug therapy may be the potential pathway of cell proliferation, migration, transformation capacity, and diffusion in lung cancer." (PMID 34299035, 2021). "Thus, SETDB1 overexpression in lung cancer cells could be crucial at different molecular levels, not only at the chromatin level." (PMID 31398867, 2019).
hepatocellular carcinoma (17 papers, 2015 to 2024). A malignant tumor that arises from hepatocytes. "Emerging evidence suggests that SETDB1 amplification and aberrant activation are significantly associated with poor prognosis in hepatocellular carcinoma (HCC), and contribute to HCC development, immune escape, and immune checkpoint blockade (ICB) resistance." (PMID 39583200, 2024). "In hepatocellular carcinoma, conversely, SETDB1 activating mechanisms at the chromosomal (copy gain at 1q21), transcriptional, and post-transcriptional levels result in SETDB1 upregulation that promotes metastasis." (PMID 37369946, 2023). "Great efforts of high-throughput sequencing have revealed that overexpression, amplification, or activation of SETDB1 plays an oncogenic effect in malignant cancers, including hepatocellular carcinoma, melanoma, and glioblastoma." (PMID 35372573, 2022). "In hepatocellular carcinoma, SETDB1 is amplified in tumor tissues and regulates the proliferation of liver cancer cells through methylation of p5347." (PMID 32393761, 2020). "Knockdown experiments of SETDB1 reduced hepatocellular carcinoma cell proliferation in vitro and suppressed orthotopic tumorigenicity in vivo." (PMID 28587163, 2017). "SETDB1 was recently found to be the most significantly up-regulated epigenetic regulator in human hepatocellular carcinomas, which also correlated with disease progression, cancer aggressiveness and poorer prognosis." (PMID 28587163, 2017). "Accumulating evidences suggest that SETDB1 might function as a novel oncogene to be involved in multiple human cancers, such as hepatocellular carcinoma, lung cancer, and sporadic cutaneous melanoma." (PMID 30309377, 2018). "Moreover, SETDB1 is also considered an oncogene in hepatocellular carcinoma (HCC) cells because it boosts their proliferation and migration via interaction with T-cell lymphoma invasion and metastasis-inducing protein 1 (Tiam1)." (PMID 36582533, 2022).
colorectal cancer (15 papers, 2018 to 2024). A primary or metastatic malignant neoplasm that affects the colon or rectum. "Overexpression of SETDB1 has been reported to correlate with aggressive features in colorectal cancer and is linked with worse survival." (PMID 33050946, 2020). "Aberrant overexpression of SETDB1 is also detected in colorectal cancer (CRC), promoting CRC cell proliferation, migration, and invasion." (PMID 38057834, 2023). "Subsequently, we verified ADORA2A expression in colorectal cancer cell lines with stable SETDB1 knockdown by qRT-PCR and western blotting, respectively." (PMID 37945707, 2023). "Clinicopathologic associations of SETDB1, a methylator of H3K9 that induces transcriptional repression, have been reported in colorectal cancer and HCC." (PMID 33050946, 2020). "Similarly, in colorectal cancer, SETDB1 overexpression facilitates cell proliferation by activating AKT, and inhibition of SETDB1 augments the sensitivity of cetuximab in colorectal cancer." (PMID 38057834, 2023). "It is also confirmed that SETDB1 could bind to the promoter of p21 and silence its expression, promoting the progression of human colorectal cancer." (PMID 35372573, 2022). "For example, in colorectal cancer (CRC), SETDB1 promotes CRC development by epigenetically silencing p21 expression." (PMID 38317200, 2024). "Overexpression of SETDB1 suppresses BAX expression and inhibits 5-fluorouracil-induced apoptosis in colorectal cancer cells." (PMID 35455671, 2022). "However, the exact pathogenesis of SETDB1 in human colorectal cancer (CRC) is hitherto unknown." (PMID 32393761, 2020). "Similarly, in colorectal cancer, overexpression of SETDB1 promotes cell proliferation by activating AKT, while inhibition of SETDB1 enhances cetuximab sensitivity in colorectal cancer therapy." (PMID 39583200, 2024). "Therefore, targeting SETDB1-mediated AKT methylation is a promising strategy for the treatment of cancers (such as skin tumor, NSCLC, and colorectal cancer)." (PMID 38057834, 2023). "In colorectal cancer cells, TIP60 also exerts an anti-inflammatory response by activating the expression of SUV39H1 and SETDB1, two histone H3K9 methyltransferases, which in turn repress the transcription of retrotransposon elements to contain STING/IRF7-mediated inflammation." (PMID 32626711, 2020).